TLR3 (toll like receptor 3)
Diseases named in the same sentence as TLR3 in open-access papers (continued):
Sharing a sentence is not in itself a finding about the gene and the disease.
pulmonary fibrosis (10 papers, 2014 to 2023). Chronic progressive interstitial lung disorder characterized by the replacement of the lung tissue by connective tissue, leading to progressive dyspnea, respiratory failure, or right heart failure. "Whereas TGFβ-dependent TG2 activation resulted in lung fibrosis in bleomycin-treated mice, the results described here showed that TLR3-dependent TG2 activation causes collagen degradation in dsRNA-treated skin." (PMID 35269849, 2022). "Interestingly, idiopathic pulmonary fibrosis patients with the Leu412Phe polymorphism in TLR3 (associated with attenuated IRF3 signaling) had accelerated lung function decline, suggesting cross-species conservation of TLR3’s role in regulating fibrosis." (PMID 32354189, 2020). "Also, heterozygous variant of the same SNP in TLR3 gene was associated with low antibody and lymphoproliferative responses to measles vaccination and with early mortality and an accelerated decline in lung function in idiopathic pulmonary fibrosis patients." (PMID 25226020, 2014). "In a bleomycin-induced model of pulmonary fibrosis, TLR3 knockout mice experienced worse outcomes, with increased pro-fibrotic cytokine release, collagen deposition and higher mortality compared to wild-type mice." (PMID 32354189, 2020). "Studies in other injury models and investigations in patients with idiopathic pulmonary fibrosis (IPF) suggest a contribution of further TLR such as TLR3, TLR7 or TLR9 in the pathogenesis of pulmonary fibrosis." (PMID 28836991, 2017). "For example, absence of the dsRNA sensor toll-like receptor 3 (TLR3) worsens bleomycin induced pulmonary fibrosis in mice and humans possessing the Leu412 Phe polymorphism in the TLR3 gene develop a rapidly progressive form of IPF." (PMID 34434962, 2021). "Hence, hypofunctional TLR3 mutations and ELMOD2 gene deficiency in IPF may contribute to progressive lung fibrosis via a decreased type I IFN response, which suggests that induction of MX1 expression in IPF is not mediated by type I IFN." (PMID 35391716, 2022). "Several proteins, including NADPH oxidase 4, Toll-like receptor 3, CCL18, matrix metalloproteinase-7, and interleukin-8, besides TGF-β, are widely accepted as key players in pulmonary fibrosis." (PMID 26415510, 2015).
Anxiety (9 papers, 2012 to 2025). Intense feelings of nervousness, tension, or panic often arise in response to interpersonal stresses. "TLR3-deficient mice have been shown to exhibit a reduced anxiety-like behaviour implying potential roles for TLR3 signaling in anxiety disorders." (PMID 31647818, 2019). "For example, systematic challenge of prenatal or neonatal mice with lipopolysaccharide (LPS; a TLR4 agonist) or poly(I:C) (a TLR3 agonist) causes autism-like (e.g. impaired social interaction) and schizophrenic-like behaviors, and increases anxiety." (PMID 31684953, 2019). "TLR3 signaling has great impact on cognition; TLR3 deficiency causes improved spatial working memory and contextual fear memory, impaired amygdala-dependent cued fear memory and anxiety." (PMID 31551681, 2019). "A similar study showed that TLR-3 deficient mice exhibit an impaired amygdala-related anxiety behavior, suggesting the possibility that TLR signaling may be normally involved in amygdala plasticity." (PMID 25687169, 2015). "In contrast, TLR3-deficient mice demonstrate impaired amygdala- and anxiety-related behavior." (PMID 23071817, 2012). "Similarly, TLR3 has been implicated with anxiety regulation." (PMID 40558558, 2025). "Finally, In contrast to TLR4 deficiency, TLR3-deficient mice exhibit impaired anxiety responses." (PMID 23071817, 2012). "In line with this, other findings showed that activation of TLR3 by poly(I:C) administration induces depressive and anxiety-like behaviors in rats." (PMID 40558558, 2025). "TLR3 mediated microglial activation and anxiety-like behaviors in female mice that were suppressed by the fatty-acid amide hydrolase 1 (FAAH) inhibitor URB597." (PMID 40558558, 2025). "Tlr3 null mice present enhanced spatial learning and memory, but also exhibit anxiety and amygdala-dependent fear memory defects." (PMID 31684953, 2019). "Maternal immune activation with the TLR3 agonist poly I:C during mid-pregnancy increases anxiety- and depressive-like behaviors." (PMID 26415953, 2016). "Notably, silencing TLR3 attenuated these effects, suggesting a pivotal role for TLR3 signaling in ethanol-induced neuroinflammation and its contribution to anxiety modulation." (PMID 40558558, 2025). "Moreover, chronic ethanol exposure upregulated TLR3 and NF-κB expression in the hippocampus, leading to neuroinflammation and anxiety-like behavior." (PMID 40558558, 2025). "Furthermore, a potential interaction between TLR3 signaling and the endocannabinoid system in anxiety regulation has been suggested." (PMID 40558558, 2025). "Mice lacking TLR3 exhibit impaired amygdala-related behavior and anxiety-like behavior in the cued fear-conditioning, open field, and elevated plus maze tasks." (PMID 40558558, 2025). "For instance, maternal immune activation via poly(I:C) to trigger TLR3 activation induced anxiety-like and schizophrenia-like behaviors in male but not female mice." (PMID 31684953, 2019).
co-infection (9 papers, 2014 to 2024). "It is concluded that Matrine possesses activity against PRRSV/PCV2 co-infection in vitro and suppression of the TLR3,4/NF-κB/TNF-α pathway as an important underlying molecular mechanism." (PMID 27080155, 2016). "This demonstrated that TLR3 is involved in the exacerbation of CL caused by SFSV co-infection." (PMID 34310619, 2021). "This raises the possibility that the increased severity of CL associated with SFSV-L. major co-infection may be triggered by TLR3-initiated pathways." (PMID 34310619, 2021). "The relative quantification of TLR-3 in different organs is higher in groups with co-infection than in groups with a single infection." (PMID 35745512, 2022). "We suggest that bacterial and viral co-infection will have a much more deleterious effect in IPF patients who have defective TLR3 function, and are 412F-heterozygous." (PMID 35148733, 2022). "During single infection and co-infection the level of expression of immune genes such as interferon and toll-like receptor 3 (TLR-3) was assessed." (PMID 35745512, 2022). "TLR3 signaling is a crucial component of the immune response to many respiratory viruses identified during viral-bacterial coinfection, and we confirmed that poly(I:C) treatment of AECs induced a vigorous antiviral response, driven by robust type I and type III IFN secretion." (PMID 37772820, 2023). "In this study, we confirmed that PRRSV/PCV2 co-infection increased both TLR3 and TLR4 expression." (PMID 27080155, 2016). "An explanation for the observed GPR15 increase in a subset of HIV-1 infected patients could be potential co-infection with another virus which may lead to additional TLR3 triggering followed by GPR15 increase." (PMID 24558379, 2014). "The mechanism of this earlier response observed during co-infection was not evaluated in this study; however, we hypothesize that PEDV/PDCoV co-infection may have a synergistic effect that led to the early up-regulation of TLR3 as compared with single infection." (PMID 36376395, 2022). "Here, we determined that SFSV co-infection with L. major results in a greater parasite load in infected mice, which manifests through an exacerbated form of CL; ostensibly, this aggravated CL is the result of a host immunopathological response that occurs through TLR3- and MAVS-dependent pathways." (PMID 34310619, 2021). "The levels of TLR-3 and IFN type I were checked at specified intervals to characterize differences between single IPNV infection and co-infection with other viruses." (PMID 35745512, 2022). "The results of this study support the existence of an early TLR3 regulatory effect induced by a single infection, while PDCoV/PEDV co-infection showed an earlier up-regulatory effect, followed by downregulation at 5 DPI." (PMID 36376395, 2022). "Matrine treatment significantly down-regulated the expression of TLR3, TLR4 and TNF-α although it, to some extent, suppressed p-IκBα expression, suggesting that TLR3,4/NF-κB/TNF-α pathway play an important role of Matrine in combating PRRSV/PCV2 co-infection." (PMID 27080155, 2016). "The expression of TLR3 in virus control was much higher than that in cell control at 12 and 24 hpi, indicating that PRRSV/PCV2 co-infection enhanced TLR3 expression." (PMID 27080155, 2016). "In the absence of TLR3, hosts are still able to clear CL caused by L. major and SFSV co-infection, in a non-prolonged time, and CL severity is lessened." (PMID 34310619, 2021). "We therefore decided to examine the role of TLR3, a dsRNA PRR, in SFSV and co-infection-induced CL." (PMID 34310619, 2021).
gastric cancer (9 papers, 2019 to 2025). A primary or metastatic malignant neoplasm involving the stomach. "In gastric cancer, TLR2 and TLR9 are thought to account for the invasive abilities of H. pylori-mediated infection, and in papillary thyroid cancer, TLR3 overactivation is linked to cancer progression." (PMID 31314777, 2019). "Emerging research suggests tumor-derived EVs may activate neutrophils in pre-metastatic niches through pathways such as toll-like receptor 3 (TLR3) signaling in lung metastasis or NF-κB induction in gastric cancer." (PMID 40574836, 2025). "In gastric cancer (GC), TLR2, TLR3, TLR4, and TLR9 are crucial for modulating immune response and tumor progression." (PMID 39451226, 2024). "In a study among 106 gastric adenocarcinoma patients, TLR3, TLR4, and TLR9 were highly expressed in gastric cancer tissues and survival worsened among patients with a high TLR3 expression." (PMID 31467388, 2019). "In gastric cancer (GC) patient models, compared to healthy volunteers, the expression of TLR-2, TLR-3, TLR-4, and TLR-9 was significantly elevated in GC patients, with higher TLR expression observed in more advanced GC subtypes." (PMID 41488647, 2025). "Therefore, our study aims to evaluate the expression of Toll-like receptors (TLR-2, TLR-3, TLR-4, and TLR-9) on NK and NKT-like cells in patients with gastric cancer (GC), compare these results with healthy volunteers (HV), and investigate variants depending on the cancer subtype." (PMID 39594809, 2024).
head and neck squamous cell carcinoma (9 papers, 2016 to 2023). A squamous cell carcinoma that arises from any of the following anatomic sites: lip and oral cavity, nasal cavity, paranasal sinuses, pharynx, larynx, and salivary glands. "TLR3 can activate NF-κB/c-Myc and increase the proliferation of head and neck squamous cell carcinoma (HNSCC) cells." (PMID 33986756, 2021). "TLR-9, TLR-5, TLR-4, TLR-3, TLR-2 and TLR-1 are linked to some clinical parameters of patients afflicted with head and neck squamous cell carcinoma (HNSCC)." (PMID 36224753, 2022). "Moreover, targeting TLR3 enabled NK cells to kill head and neck squamous cell carcinoma (HNSCC) by secreting IFNγ." (PMID 34124272, 2021). "Indeed, in TLR3-positive head and neck squamous cell carcinoma (HNSCC), the synthetic dsRNA reduced survivin levels in a dose- and TLR3-expression-dependent manner." (PMID 33147700, 2020). "Finally, TLR3 and TLR4 expression was observed in head and neck squamous cell carcinoma (HNSCC)." (PMID 27191981, 2016).
myeloma (9 papers, 2013 to 2025). "According to previous studies, activating TLR3-TICAM1 pathway could inhibit the progression of tumor cells in multiple myeloma." (PMID 35933370, 2022). "Previous studies proved that activating TLR3/TICAM1 signaling could suppress multiple myeloma progression." (PMID 35933370, 2022). "Immune cells can efficiently affect myeloma cells via stimulation with TLR3 agonists." (PMID 33986756, 2021). "Many studies have investigated the roles of TLR3 in multiple myeloma (MM)." (PMID 33986756, 2021). "Activation of TLR3 resulted in increased proliferation in human myeloma cells." (PMID 27941651, 2016). "However, whether TLR3 mediates the antitumor immunity induced by the inflammatory response in myeloma cells remains to be elucidated." (PMID 40562746, 2025). "Analysis of toll-like receptor (TLR) expression at protein level indicated that TLR1, TLR3, TLR4, TLR7, TLR8, and TLR9, were similarly expressed in most human myeloma cell lines, including L363 and RPMI 8226 cells, as well as in primary cells from MM patients." (PMID 28702457, 2017). "Expression of mRNA for TLR1, TLR3, TLR4, TLR5, TLR7, TLR8, and TLR9 was found in all myeloma cell, but levels of mRNA expression differed amongst different cell lines." (PMID 23593278, 2013). "Among these TLR3-expressing myeloma cell lines, the effects of poly (I:C) stimulation are not consistent." (PMID 33986756, 2021).
viral hepatitis (9 papers, 2010 to 2024). An acute or chronic inflammation of the liver parenchyma caused by viruses. "Pregnant patients with high levels of TLR3 and a robust IFN-γ response exhibit acute viral hepatitis cases with limited disease progression and rapid recovery, whereas patients with lower expression of TLR3 and IFN-γ progress to ALF." (PMID 29255453, 2017). "Notably, the search results in the PPI network of key target protein of the intersection targets showed that TLR3, TBK1, IRF3, IL6, were important targets associated with viral hepatitis." (PMID 38322849, 2024). "Besides, TLR3, TBK1, IRF3, IL6, were important targets associated with viral hepatitis." (PMID 38322849, 2024). "The TLR3 pathway plays an important role in influencing host innate immunity and viral clearance during viral hepatitis infection, and may represent a useful therapeutic approach for the treatment of viral hepatitis." (PMID 20936107, 2010). "High levels of TLR3 and anti-and pro-inflammatory cytokines; IFNγ, TNF-α, IL10, and TGF-β in acute viral hepatitis patients compared to acute liver failure patients were found to play an important role in HEV disease pathogenesis." (PMID 34502167, 2021). "Clinically, a higher level of TLR3 expression along with anti- and pro-inflammatory cytokines was observed in peripheral blood mononuclear cells (PBMC) of HEV infected patients with acute viral hepatitis compared to patients with acute liver failure." (PMID 34502167, 2021). "Patients with high levels of TLR3 and robust IFN-γ response are observed in self-limiting acute viral hepatitis cases, and are able to limit the disease and recover uneventfully." (PMID 27656178, 2016).
allergic asthma (8 papers, 2005 to 2024). A asthma with a basis in a pathological type I hypersensitivity reaction. "Appropriate activation of host defense by a TLR3 agonist could be a therapeutic option for those with IP deficiency who may be more susceptible to allergic asthma worsened by rhinovirus infection." (PMID 39339860, 2024). "TLR3 activation by poly (inosinic-cytidylic) acid in an established experimental allergic asthma mice model increased the release of proinflammatory cytokines and mucus production which was also associated with increased production of IL-17A by NK cells." (PMID 34394070, 2021). "TLR3 activation in an established experimental allergic asthma mice model increased the release of proinflammatory cytokines and mucus production which was also associated with the increased production of interleukin 17 (IL-17A) by natural killer (NK) cells." (PMID 34394070, 2021). "One possible explanation for the protective mechanism of OK-432 in allergic asthma is the induction of IFN-γ via TLR3/4 signaling." (PMID 30402504, 2018). "Down-regulation of TLR3 expression using siRNAs in rats caused a decrease of serum IgE levels and a reduction of IL4 mRNA expression in immune organs in an allergic asthma model." (PMID 23882263, 2013). "The present study was designed to evaluate the effect of concomitant TLR3 and TLR4 stimulation in a murine model of allergic asthma." (PMID 26494305, 2015). "We tested the effect of agonists of TLR2 (P40 protein of Klebsiella pneumoniae and the Pam3Cys lipopeptide), TLR3 (double-stranded RNAs Poly(I∶C)), TLR4 (LPS and lipid A) and TLR7 (R848) on experimental allergic asthma and autoimmune diabetes in the NOD mouse." (PMID 20628601, 2010). "Recruitment and activation of neutrophils, macrophages, and Th1 cells mediated by viral TLR-3 ligation combined with IL-8 and RANTES may imply an important role of viral exacerbations of allergic asthma and COPD." (PMID 24498371, 2014). "It is important to note that in this study, mice were sensitized to and subsequently challenged with OVA (ovalbumin) and thus the role of TLR3 in regards to fungal induced allergic asthma has never been studied in any great detail." (PMID 23882263, 2013).
cardiac hypertrophy (8 papers, 2020 to 2025). "S-nitrosylation of muscle LIM protein (MLP) induces TLR3-mediated RIP3 and nucleotide-binding oligomerization domain-like receptor pyrin domain containing 3 (NLRP3) inflammasome activation, thereby promoting the development of myocardial hypertrophy." (PMID 37113698, 2023). "Under pressure overload, S-nitrosylation of muscle LIM protein (MLP) increased the complex formation between toll-like receptor 3 (TLR3) and receptor-interacting protein kinase 3 (RIP3), inducing NLRP3 inflammasome activation, and promoting the development of myocardial hypertrophy." (PMID 35509275, 2022). "They examined the SNO-MLP level in myocardial samples acquired from patients diagnosed with myocardial hypertrophy, transverse aortic constriction (TAC) mice, angiotensin II/phenylephrine-treated neonatal rat cardiomyocytes, and TLR3 (Toll-like receptor 3) knockout mice." (PMID 33126514, 2020).